CD4 (CD4 molecule)
Diseases named in the same sentence as CD4 in open-access papers (continued):
Sharing a sentence is not in itself a finding about the gene and the disease.
Nephropathy (20 papers, 2011 to 2025). A nonspecific term referring to disease or damage of the kidneys. "On the other hand, patients with nephropathy due to other causes have a significant positive correlation between T lymphocytes and CD4+ T cells with serum albumin concentration." (PMID 40277801, 2025). "The proportion of CD4+CD8+ DPT cells was an independent risk factor for nephropathy in SLE patients (odds ratio [OR], 5.136; 95% confidence interval [CI], 2.115–12.473; P<0.001)." (PMID 36625011, 2022). "Downregulation of CD4+ T-cell subsets caused by the CC genotype could protect against the initiation of BKV-associated nephropathy." (PMID 36297195, 2022). "When nephropathy due to other causes in end-stage CKD origin is considered, serum albumin concentration positively correlates with T lymphocytes and helper CD4+ T cells." (PMID 40277801, 2025). "Several studies have shown an increase in the proportion of CD4+/CD8+ T cells in PMN patients, with the CD4+/CD8+ ratio gradually decreasing with the clinical remission of nephropathy." (PMID 38448810, 2024). "They found that a lack or low levels of BKPyV-specific CD4 and CD8 T cells were associated with an increased risk of persistent viremia, florid BKPyV nephropathy, and the urgent need for a reduction in immunosuppression." (PMID 38791055, 2024). "The progression of BKV infection to BKV-associated nephropathy is mediated by infiltration and strong inflammation caused by CD8+ and CD4+ T cells." (PMID 36297195, 2022). "The number of CD4+CD25+ cells tended to gradually decrease with increasing severity of histologically assessed nephropathy." (PMID 27278520, 2016). "These metabolites not only improve the function of regulatory T cells and promote the proliferation of CD4+ effector T cells but also reduce levels of inflammatory cytokines in both serum and major organs, alleviate kidney damage, and improve coagulation function and vasodilation." (PMID 41194878, 2025). "With respect to the IKK1 pathogenic role in IRI and its importance for the CD4+T cells differentiation process, we next investigated as to whether pharmacological block of IKK1 could alleviate kidney damage." (PMID 37074502, 2023). "Th17 is a new type of effector CD4+ T-cell in the IL-17 signaling pathway that secretes IL-17A, which can promote the secretion of proinflammatory factors and macrophage infiltration, thereby exacerbating kidney damage in DN." (PMID 35755045, 2022). "Furthermore, with increasing severity of histologically assessed nephropathy, the number of CD4+CD25+ cells tended to gradually decrease." (PMID 27278520, 2016). "Furthermore, although the use of lymphocyte-depleting agents is classically associated with BKPyV-nephropathy, we did not observe this association, even looking at the number of total lymphocytes or CD4+ lymphocytes." (PMID 40872883, 2025). "As for the adult population, in a recent pediatric study, high levels of BKPyV-specific CD4 and/or CD8 T-cells were found in cases of self-limiting viremia, whereas a lack or low level of BKPyV-specific T cells was associated with long-term viremia and florid BKPyV nephropathy." (PMID 38791055, 2024). "Activated CD4 and CD8 T cells and their effector functions are hypothesized to be the key players in immune-mediated kidney damage in LN62,63." (PMID 34996983, 2022).
respiratory failure (20 papers, 2008 to 2025). The significant impairment of gas exchange within the lungs resulting in hypoxia, hypercarbia, or both, to the extent that organ tissue perfusion is severely compromised. "This loss of Treg/CD4 T cell coordination is clinically consequential, as Treg deficiency exacerbates inflammation and impairs Th17/Treg balance—a dysregulation linked to respiratory failure and poor Long COVID outcomes." (PMID 41141591, 2025). "The CAT score, home oxygen therapy, and CD4+CD8+ T cells% were identified as significant predictors of respiratory failure in AECOPD patients." (PMID 38031059, 2023). "In this prospective, longitudinal, observational trial, the CAT score, home oxygen therapy, and CD4+CD8+ T cells% were significant predictors of respiratory failure in AECOPD patients." (PMID 38031059, 2023). "Significantly increased SARS-CoV-2-induced IFN-γ, IL-2, and TNF-α production were seen in CD4 + T cells from patients with neurologic involvement and respiratory failure." (PMID 36093351, 2022). "Coinfection with P. jirovecii and SARS-CoV-2 has been reported in a patient with progressive hypoxemic respiratory failure and CD4+ lymphocytopenia." (PMID 34287033, 2021). "The COPD Assessment Test (CAT) score combined with home oxygen therapy and CD4+CD8+ T cells% to predict respiratory failure in AECOPD patients were the best (the area under the curves [AUC] = 0.77, 95% CI: 0.70–0.86, P < 0.0001, sensitivity: 60.4%, specificity: 86.8%)." (PMID 38031059, 2023). "ROC analyses for home oxygen therapy prediction of respiratory failure showed a moderate, although significant, prediction (AUC = 0.64, P < 0.01); ROC analyses for CD4+CD8+ T cells% showed similar results (AUC = 0.63, P < 0.02, sensitivity: 47.9%, specificity: 75.0%, Cov ≤ 0.61)." (PMID 38031059, 2023). "Moreover, we found that the CAT score combined with home oxygen therapy and CD4+CD8+ T cells% to predict respiratory failure in AECOPD patients were the best (AUC = 0.77, 95% CI: 0.70–0.86, P < 0.0001, sensitivity: 60.4%, specificity: 86.8%)." (PMID 38031059, 2023). "One interesting finding was that lower proportions of CD4+CD8+ T cells seem sociated with worse outcomes, including respiratory failure, re-admission, and NIV." (PMID 38031059, 2023). "The nomogram model’s construction aimed to predict respiratory failure in patients with AECOPD, utilizing variables such as home oxygen therapy, CAT score, and the percentage of CD4+CD8+ T cells." (PMID 38031059, 2023). "The nomogram model, developed to forecast respiratory failure in patients with AECOPD, utilizing variables such as home oxygen therapy, CAT score, and CD4+CD8+ T cells%, demonstrated a high level of practicality in clinical settings." (PMID 38031059, 2023). "In this study, the authors evaluated the etiology of respiratory failure among HIV-infected patients requiring ICU admission, its relationship with their CD4 lymphocyte count as well as the use of HAART, and its impact on outcome." (PMID 24065988, 2013). "We report a young patient admitted with diabetic ketoacidosis characterized by rapidly progressing acute respiratory failure with negative pathogen blood cultures, serum antibodies and polymerase chain reaction results, and a normal CD4+ lymphocyte count." (PMID 41070051, 2025). "Considering that using the nomogram in detecting a respiratory failure in AECOPD patients to direct clinical management was rapid and cost-effective, we developed this prediction model incorporating variables such as home oxygen therapy, CAT score, and CD4+CD8+ T cells percentage." (PMID 38031059, 2023).
varicella (20 papers, 2010 to 2025). "In contrast, loss of CD8 T cells led to a slightly higher peak viral load and the loss of CD4 T cells led to significantly higher viral loads and disseminated varicella." (PMID 22102814, 2011). "Measles-mumps-rubella and varicella vaccines are recommended only in the presence of a CD4 lymphocyte count ≥ 200/mL." (PMID 37631883, 2023). "Chickenpox and furuncle were found in stage 1 of the disease with a mean CD4+ cell count of >500 cells/mm3." (PMID 34513432, 2021). "However, in healthy individuals, protection from varicella often persists even after antibody levels decline to undetectable levels, suggesting that CD4+ T cell responses play a critical role in long-term protection." (PMID 40432143, 2025). "These cytokines correlate with mild varicella, whereas cell-mediated immunodeficiency (low and depleted VZV-specific CD4 and CD8 T-cell responses) may also be associated with severe shingles." (PMID 37784014, 2023). "No life-threatening adverse events were observed, although one patient suffered from vaccine-strain varicella who showed cellular and humoral immunodeficiency (CD4 cell counts = 511/mm3, stimulation index of lymphocyte blast transformation by PHA = 91.1, serum IgG level = 208 mg/dl)." (PMID 33002085, 2020). "Of 67 reports with CD4 counts available, 41 (61%) described persons immunocompromised at time of vaccination (CD4 count <500 cells/mm3), and differed from overall reports only in that varicella was the most common live virus vaccine (4 reports)." (PMID 29920551, 2018). "In contrast, CD4 depletion led to higher viral loads, prolonged viremia and disseminated varicella." (PMID 22102814, 2011). "Finally, depletion of CD4 T cells resulted in disseminated varicella, higher viral loads and sustained viremia although complete CD4 T cell depletion was not achieved until 10 dpi." (PMID 22102814, 2011). "We conclude that the analysis of VZV-specific CD4+ T-cells might support the rapid diagnosis of primary varicella under certain circumstances, as for example in cases of atypical or subclinical varicella or in the absence of detectable VZV DNA in plasma." (PMID 20205920, 2010). "Although there is a paucity of data from clinical trials on the use of varicella vaccines in adolescents and adults infected with HIV, the CDC recommends that PLH who are >8 years old with CD4 counts ≥ 200 cells/mm3 would benefit from receiving two doses of Varivax 3 months apart." (PMID 39066418, 2024). "People living with HIV who are varicella non-immune and have CD4 count > 200 cells/mm3 should be given two doses of the live attenuated varicella vaccine (Varivax) 3 months or more apart." (PMID 35456055, 2022). "Another study described VZV-specific CD4 T cells in the skin of aged subjects with a history of varicella but not HZ45, suggesting VZV-specific T cells are long-lived in skin." (PMID 36376285, 2022). "For example, in partial CID, the CDC recommends avoidance of all live vaccines, while the Canadian Immunization Guide suggests that patients with a CD4 + T cell count > 0.500 × 109/L and normal mitogen responses can receive MMR and univalent varicella vaccines." (PMID 35397595, 2022). "CD4 depleted animals experienced severe and disseminated varicella rash, which also did not begin to heal until 42 dpi." (PMID 22102814, 2011). "Although antibody titers serve as a useful marker of varicella immunity, they may not fully capture vaccine-induced protection due to the critical role of CD4+ T cells in the immune response to VZV." (PMID 40432143, 2025). "In sharp contrast, the lack of CD4 T cells leads to disseminated varicella." (PMID 22102814, 2011). "Measles, mumps, rubella (MMR) and varicella (VAR) are not recommended in pregnant women and immunocompromised patients (excluding HIV), and for PLHIV with a CD4 count of <200 mm3, while HPV is contraindicated in pregnant women." (PMID 35844850, 2022).
varicella (continued). "In a nonhuman primate model with simian varicella virus infection, it was shown that depletion of CD4+, and not CD8+, T cells resulted in significantly higher viral loads and disseminated varicella, while the absence of B cells did not alter disease severity." (PMID 35935972, 2022).
Cerebral ischemia (19 papers, 2010 to 2025). Restriction of arterial blood supply to the brain associated with insufficient oxygenation to support the metabolic requirements of the tissue. "In addition, immunodepletion of CD4+ lymphocyte cells in mice increased neuronal loss and was associated with more severe neurological deficits 7 days after focal brain ischemia." (PMID 33922467, 2021). "T cells, particularly CD8+ and γδT cells, are known to be critical T cell subsets associated with detrimental effects, while CD4+ Th2 and CD4+ Treg cells are associated with protective effects in the surrounding neural parenchyma after cerebral ischemia or degenerative diseases upon activation." (PMID 25658950, 2015). "Previous studies have shown that stress triggered by cerebral ischemia‒reperfusion injury leads to the infiltration of CD4+ T cells into the cerebral cortex and hippocampus." (PMID 39630234, 2025). "Studies demonstrate that cerebral ischemia-induced cognitive decline correlates with altered peripheral T-cell immunity, characterized by reduced CD4+ regulatory T (Treg) cells and expanded CD8+ effector T cells." (PMID 41291751, 2025). "In FasL mutant (gld) mice subjected to focal brain ischemia, the percentage of CD4+ T cells in peripheral blood was decreased when compared to that in wild-type animals." (PMID 31654316, 2020). "Another study also demonstrated that the CD4+T/CD8+T cell ratio increased in cerebral ischemia/reperfusion injury sites." (PMID 31024567, 2019). "Previous evidence shows that activated and infiltrated microglia/macrophages after cerebral ischemia can stimulate activated CD4 + T cells to differentiate into Th1 or Th2 cells, which then produce proinflammatory or anti-inflammatory cytokines to damage or protect the brain." (PMID 35432523, 2022). "Evidence supports a beneficial function of CD4+ lymphocyte cells in experimental brain ischemia." (PMID 33922467, 2021). "Alternatively, low CD4+ T-cell counts might represent a surrogate marker that is closely related to the magnitude of multiple immunosuppressive effects induced by cerebral ischemia." (PMID 20090932, 2010). "CD8 + T lymphocytes are involved in neuronal cell injury through the release of cytotoxic proteases, and CD4 + and CD8 + T cells can increase IS and brain injury after cerebral ischemia and reperfusion by increasing inflammatory responses and thrombosis." (PMID 38995420, 2024). "Both CD4+ and CD8+ T-cells aggravated brain ischemia/reperfusion injury via inflammatory and thrombogenic responses, resulting in larger infarct volumes and greater neurological deficits." (PMID 35645988, 2022). "Although the mROS and mitochondrial weight of CD4+ T cells treated with astilbin for 24 h showed no obvious changes, they decreased after 36-h treatment, confirming the protective role of astilbin in cerebral ischemia/reperfusion injury by downregulating ROS-NLPR3 activation." (PMID 35652039, 2022).
clear cell renal cell carcinoma (19 papers, 2003 to 2025). "The sKGs, CD74 expression in clear cell renal cell carcinoma (ccRCC) cells has shown to be significantly associated with high infiltration of CD4 + T cells, which may have important implications for the tumor microenvironment and immune response." (PMID 40834023, 2025). "Single-cell RNA data of clear cell renal cell carcinoma (ccRCC) treated with anti-PD-1 were obtained from public databases, then 27,707 high-quality CD4 + T and CD8 + T cells were obtained for subsequent analysis." (PMID 36982415, 2023). "High PCIF1 expression exhibited a positive correlation with CD4+ T cell infiltration specifically in renal clear cell carcinoma." (PMID 38162499, 2023). "It was reported that CD4+T cells can induce EMT-like features in clear cell renal carcinoma cells by secreting IL-6." (PMID 36186418, 2022). "Comprehensive analysis of immune infiltration in the TIMER database correlated PTP4A3 expression with the infiltration of B cells, CD8+ T cells, CD4+ T cells and neutrophils in both clear cell renal cell carcinoma and papillary renal cell carcinoma." (PMID 34630392, 2021). "In clear cell renal cell carcinoma, resting mast cells are positively correlated with MUC20 level in the tumor immune microenvironment, while MUC20 expression is negatively linked with activated CD4+ memory T cells." (PMID 38564630, 2024). "In summary, we have shown that increased intratumoural CD4+ T-lymphocyte infiltrate was associated with poor outcome, independent of grade, in patients with renal clear-cell cancer." (PMID 14612901, 2003). "Clear cell renal cell carcinoma (ccRCC) are characterized by rich leukocyte infiltrates, which often consist of CD8+T cells, CD4+ T cells, natural killer cells and myeloid cells." (PMID 37803307, 2023). "And in clear cell renal cell carcinoma (ccRCC), CMTM6 silencing leads to increased CD4 + and CD8 + T cell infiltration in mouse models, which in turn promotes anti-tumor immunity." (PMID 36698778, 2022). "Interestingly, high ST8SIA1 expression has been correlated with the increased infiltration of CD4+ and CD8+ T cells, neutrophils, dendritic cells, and M1 macrophages in clear-cell renal cell carcinoma." (PMID 39860532, 2025). "Also, our group described significantly lower CD4+, CD8+, and CD45+ infiltrates in CTLA4 promoter hypermethylated clear cell renal cell carcinomas." (PMID 37415208, 2023). "Immune infiltration analysis indicates that cytoskeleton-associated protein 2-like protein may affect the level of activated CD4+ memory T cells, M1 macrophages, CD8+ T cells, and neutrophils in clear cell renal cell carcinoma." (PMID 36699449, 2022). "The results of the present study show that an increase in CD4+ but not CD8+ T-lymphocyte infiltrate, as assessed by immunohistochemistry, was associated with poor cancer-specific survival, independent of grade, in patients undergoing potentially curative surgery for renal clear-cell cancer." (PMID 14612901, 2003).
cognitive decline (19 papers, 2016 to 2025). "In PWH the correlation between the APOEε4 allele and cognitive decline seems to be influenced by CD4+ cell count nadir." (PMID 35353274, 2022). "Our results agree with this interpretation as the early stages of cognitive decline, and the multiple possible disease etiologies causing that decline in our study participants could lead to mixed CD4+ and CD8+ responses in our group analysis." (PMID 38867294, 2024). "Specifically, the CD4 transcript, which has been previously shown to promote neuroinflammation and cognitive decline in AD, appeared as the most differentially expressed gene between resilient- and demented mice." (PMID 34502030, 2021). "In AD patients, its dysregulation may alter CD4+ T cell activation and recruitment, leading to neuroinflammation and subsequent cognitive decline." (PMID 40560886, 2025). "Notably, a recent study of elderly patients reported enhanced JAK/STAT3 signaling responses in CD4 + and CD8 + T cell in patients at greater risk for cognitive decline after surgery." (PMID 39953524, 2025). "Improvements in immune status, particularly the recovery of CD4+ counts, as well as higher educational attainment, may play a critical role in mitigating cognitive decline." (PMID 39944538, 2025). "The role of the CD4/CD8 ratio in understanding the underlying pathogenic conditions such as T-cell pathogenesis and its associations with patterns of brain atrophy or cognitive decline has been discussed previouly." (PMID 40458466, 2025). "In addition, higher proportions of CD4+ naive cells were identified in patients with less cognitive decline and we found a slight increase in B memory cells in those who were more symptomatic at baseline." (PMID 38212355, 2024). "Yet, it is unclear if changes in CD8+ TEMRAs are an AD-specific phenotype or are seen more generally with cognitive decline, and if the changes are limited to CD8+ T cells or are also seen in CD4+ T cells." (PMID 38867294, 2024). "Previous research has demonstrated that patients with AD exhibit a significant reduction in CD8+ T cell subsets, a significant increase in CD4+ helper T cells, and a significant correlation between the CD4/CD8 ratio and cognitive decline that is characteristic of AD." (PMID 37920383, 2023). "Similarly, a significant correlation between CD4 transcript and MMSE score was observed (Spearman’s correlation, r = −0.35, p value = 0.01) suggesting a possible link between peripheral CD4 mRNA and cognitive decline." (PMID 34502030, 2021). "Antibiotic-treated mice that survive systemic Lm infection have increased numbers of CD8+ and CD4+ T-lymphocytes in the brain that include tissue resident memory (TRM) T cells, but post-infectious cognitive decline has not been demonstrated." (PMID 37143648, 2023).